CLEC11A (C-type lectin domain containing 11A)
Description:
Promotes osteogenesis by stimulating the differentiation of mesenchymal progenitors into mature osteoblasts. Important for repair and maintenance of adult bone (By similarity).
Synonyms: CLECSF3; LSLCL; SCGF; P47
Tractability: Antibody: UniProt places it where antibodies can reach, with high confidence; its Gene Ontology location is reachable by antibodies, with high confidence; UniProt predicts a signal peptide or a membrane-spanning region. PROTAC: ubiquitination databases record sites on it.
Gene: Protein-coding gene on chromosome 19 (50,723,286 to 50,725,719, forward strand). Ensembl gene ENSG00000105472.
Subcellular location: Cytoplasm; Secreted
Subcellular location (Human Protein Atlas): Centrosome; Predicted to be secreted
Gene Ontology:
Molecular function: growth factor activity; protein binding; carbohydrate binding
Biological process: positive regulation of cell population proliferation; ossification; signal transduction
Cellular component: cytoplasm; extracellular region
Genetic constraint (gnomAD): Loss-of-function variants: 35 observed, 29.43 expected, observed/expected ratio (o/e) 1.19, 90% interval 0.91 to 1.58. The synonymous counts are far from expectation, so gnomAD's model fits this gene poorly and the ratio says little. Missense variants: 519 observed, 401.37 expected, observed/expected ratio (o/e) 1.29, 90% interval 1.2 to 1.39. Synonymous variants: 220 observed, 173.54 expected, observed/expected ratio (o/e) 1.27, 90% interval 1.13 to 1.42.
Homologues: Orthologues: chimpanzee CLEC11A (99% identical), macaque CLEC11A (98% identical), dog CLEC11A (90% identical), mouse Clec11a (85% identical), pig CLEC11A (84% identical), guinea pig CLEC11A (83% identical), rat Clec11a (72% identical), tropical clawed frog clec11a (32% identical), zebrafish clec11a (32% identical). Paralogues in human: CLEC3A (19% identical), CLEC3B (19% identical).
Diseases named in the same sentence as CLEC11A in open-access papers:
CLEC11A is named in the same sentence as 55 diseases in open-access papers, as found by Europe PMC text mining. Sharing a sentence is not in itself a finding about the gene and the disease. The quoted sentences say what the papers report.
multiple myeloma (8 papers, 2016 to 2025). "CLEC11A is linked to the development of a variety of cancers, including leukemia, multiple myeloma, and gastrointestinal tumors." (PMID 33613623, 2020). "Additionally, CLEC11A is associated with the pathogenesis of several tumors, such as lung cancer, gastrointestinal tumors, multiple myeloma, and leukemia." (PMID 40294019, 2025). "Molecular and clinical data from 450 patients with multiple myeloma measured using a network biology approach confirmed that Clec11a serves as a novel modulator and candidate target for the treatment of myeloma." (PMID 39188913, 2024). "A recently published CoMMpass study demonstrated that, by using an integrative network biology analysis, CLEC11A was found to be a novel regulator and a candidate of therapeutic target in in multiple myeloma." (PMID 30246025, 2018). "In conclusion, Clec11a may have great potential in the treatment of bone diseases, including chronic bone diseases, such as OA and OP, as well as osteosarcoma, multiple myeloma, and other diseases." (PMID 39188913, 2024). "Within these six immune genes, CLEC11A was the driver gene in multiple myeloma (MM)." (PMID 32352015, 2020). "Meanwhile, CLEC11A has emerged as a new regulator and potential therapeutic target of multiple myeloma, especially within the SET domain-related myeloma context." (PMID 37597212, 2024).
leukemia (7 papers, 2011 to 2025). A malignant (clonal) hematologic disorder, involving hematopoietic stem cells and characterized by the presence of primitive or atypical myeloid or lymphoid cells in the bone marrow and the blood. "The initial studies on CLEC11A (previously named SCGF) implicated its role in the survival of leukemia cells." (PMID 35267664, 2022). "C-type lectin 11A (CLEC11A, also named stem cell growth factor (SCGF)) is originally identified as an autocrine factor secreted by leukemia cell lines." (PMID 35267664, 2022). "The analysis about CLEC11A-associated gene expression differential was performed to investigate the biological role of CLEC11A in the pathogenesis of leukemia by comparing the RNA expression levels of CLEC11A low expression group and high expression group." (PMID 33747924, 2021). "This analysis showed that CLEC11A expression was higher in breast, colorectal, gastric, pancreatic cancers and leukemia, lymphoma, sarcoma tumors than in normal tissues." (PMID 33747924, 2021). "The neutralization antibody against CLEC11A induces cell death in multiple leukemia cell lines." (PMID 35267664, 2022). "This study demonstrated that CLEC11A is an upregulated gene and might be crucial in the progress of leukemia." (PMID 33747924, 2021). "Multiple public databases revealed that CLEC11A expression was higher in leukemia." (PMID 33747924, 2021). "C-type lectin domain family 11 member A (Clec11a), as a growth factor for hematopoietic progenitor cells, activates the expression of osteoblast-related gene transcripts, including Alp, Runx2, LEF1, and Axin, and is associated with the development of several cancers, such as leukemia." (PMID 32872365, 2020).
osteoporosis (6 papers, 2016 to 2025). A condition of reduced bone mass, with decreased cortical thickness and a decrease in the number and size of the trabeculae of cancellous bone (but normal chemical composition), resulting in increased fracture incidence. "Further experiments revealed that injections of Clec11a could fully restore the bone deficiencies seen in both Clec11a knockout mice and mice that displayed the symptoms of osteoporosis." (PMID 27960074, 2016). "More importantly, Clec11a has high therapeutic potential for treating various bone diseases and can enhance the therapeutic effects of the parathyroid hormone against osteoporosis." (PMID 39188913, 2024). "Another intriguing study demonstrated that MSC-EVs loaded with recombinant C-Type lectin domain family 11, member A (CLEC11A) facilitate the transition of BM-MSC from lipogenic to osteogenic differentiation and inhibit osteoclast activity, ultimately alleviating osteoporosis." (PMID 38697996, 2024).
breast carcinoma (4 papers, 2016 to 2025). "From the clinical information in the TCGA database, we found that a significant increase of CLEC11A also occurred in other types of carcinomas, such as head and neck cancer and breast cancer." (PMID 35267664, 2022). "Although the current research on CLEC11A in breast cancer is limited, it may become a potential prognostic and immune biomarker for the disease." (PMID 40860340, 2025). "In addition to LAC, CLEC11A expression levels were also higher in breast cancer (BRCA) and head and neck squamous carcinoma (HNSC) tissues based on the clinical data in the TCGA." (PMID 35267664, 2022).
lung carcinoma (4 papers, 2011 to 2025). "We identified that CLEC11A, an extracellular C-type lectin, was over-expressed in lung cancer cell lines harboring mutated EGFR." (PMID 35267664, 2022). "In summary, our study showed that CLEC11A expression is increased in lung cancer cell lines and lung cancer tissues harboring mutated EGFR." (PMID 35267664, 2022). "Specifically, Lin and colleagues showed that CLEC11A-expressing lung cancer cells have increased tumor growth in mice and inhibiting CLEC11A expression prevented tumor growth." (PMID 38466706, 2024). "CLEC11A-expressing lung cancer cells have been shown to promote the growth of tumors in mice while inhibition of CLEC11A expression prevented tumor growth." (PMID 38466706, 2024). "Our results indicated that CLEC11A was a factor of angiogenic potential and was involved in lung cancer tumorigenesis." (PMID 35267664, 2022). "We also detected higher levels of CLEC11A proteins in lung cancer cell lines harboring an endogenous EGFR kinase domain mutation." (PMID 35267664, 2022).
acute myeloid leukemia (3 papers, 2021 to 2024). Acute myeloid leukemia (AML) is a group of neoplasms arising from precursor cells committed to the myeloid cell-line differentiation. "Abnormalities in the methylation and expression of CLEC11A have been correlated with the prognosis of pancreatic cancer and acute myeloid leukemia (AML)." (PMID 37597212, 2024). "CLEC11A, formerly known LSLCL with homologous protein SCGF, is thought to be involved in early hematopoiesis and was detected in immature neutrophils in patients with chronic and acute myeloid leukemia as well as other hematologic disorders." (PMID 34727888, 2021).
gastric cancer (3 papers, 2024 to 2025). A primary or metastatic malignant neoplasm involving the stomach. "In gastric cancer, overexpression of CLEC11A is associated with poor prognosis." (PMID 40860340, 2025). "However, the involvement of CLEC11A in gastric cancer (GC) is not well understood." (PMID 38348052, 2024).
cholangiocarcinoma (2 papers, 2024). A carcinoma that arises from the intrahepatic biliary tree (intrahepatic cholangiocarcinoma) or from the junction, or adjacent to the junction, of the right and left hepatic ducts (hilar cholangiocarcinoma). "We observed that the CLEC11A expression was significantly elevated in breast invasive carcinoma, cholangiocarcinoma, colon adenocarcinoma, head and neck squamous cell carcinoma, LUAD, prostate adenocarcinoma, and STAD." (PMID 37597212, 2024). "The high expression of CLEC1B, CLEC3B and CLEC11A are closely related to the good survival of cholangiocarcinoma." (PMID 39553729, 2024).
Cirrhosis (2 papers, 2023). A chronic disorder of the liver in which liver tissue becomes scarred and is partially replaced by regenerative nodules and fibrotic tissue resulting in loss of liver function. "Through a detailed analysis of the association between cirrhosis status, liver etiology, gender, age, and tumor size with DNA methylation changes, we identified DNA methylation changes in HOXA1-, CLEC11A-, AK055957-, and TSPYL5-associated clinical risk factors." (PMID 37835478, 2023). "In summary, the data from MeD-seq confirmed the results of qMSP that non-cirrhotic HCC had the highest methylation levels of HOXA1, CLEC11A, and TSPYL5 compared to hepatitis, benign lesions, and cirrhosis." (PMID 37835478, 2023). "Although the individual biomarkers HOXA1, CLEC11A, and AK055957 poorly discriminated between cirrhotic HCC and cirrhosis with 47–60% sensitivity (AUCs 0.52–0.72), the combination of DMMs demonstrated higher AUCs compared to single biomarkers (AUCs 0.84–0.86)." (PMID 37835478, 2023). "In summary, we found that patients with non-cirrhotic HCC exhibited aberrant DNA methylation levels in liver tissue for HOXA1, CLEC11A, AK055957, and TSPYL5 as compared to hepatitis, benign lesions, and cirrhosis." (PMID 37835478, 2023). "Notably, the median methylation scores of HOXA1, CLEC11A, and TSPYL5 were higher in cirrhotic HCC compared to cirrhosis, hepatitis, and benign lesions, although only CLEC11A exhibited a statistical difference (p < 0.05)." (PMID 37835478, 2023).
osteosarcoma (2 papers, 2022 to 2024). A usually aggressive malignant bone-forming mesenchymal neoplasm, predominantly affecting adolescents and young adults. "Naïve IGHD+ B and immune regulatory IGHA1+ B cells were largely identified in MPE, whereas bone metabolism‐related CLEC11A+ B cells were significantly enriched in osteosarcoma PT." (PMID 36305631, 2022). "In the current scRNA‐seq study of advanced osteosarcoma tissues, we noticed four main B cell sub‐clusters, including the conventional naïve B cells, regulatory B cells, plasma B cells and a novel CLEC11A+ B cell sub‐cluster." (PMID 36305631, 2022). "By performing scRNA-Seq on advanced osteosarcoma tissues, a novel Clec11a B cell subpopulation with high expression of Clec11a, MMP-9, and bone-bridging proteins was identified, suggesting that Clec11a B cells may be involved in bone metabolism." (PMID 39188913, 2024). "Interestingly, B cells in TNF‐Tg SBM also show increased levels of C‐type lectin domain family gene CLEC4D and CLEC4E, suggesting that the CLEC11A+ B cells in osteosarcoma may have similar biological functions as the TNF‐Tg SBM‐derived B cells." (PMID 36305631, 2022). "Thus, Clec11a B cells may represent an emerging target for osteosarcoma treatment." (PMID 39188913, 2024).
anemia (1 paper, 2024). A reduction in the number of red blood cells, the amount of hemoglobin, and/or the volume of packed red blood cells. "As a growth factor, the C-type lectin domain family 11 member A (CLEC11A) plays important roles in regulating hematopoietic differentiation and homeostasis, safeguarding against lipotoxicity and severe malaria anemia, and maintaining bone homeostasis." (PMID 38348052, 2024).
chordoma (1 paper, 2015). Chordomas are rare malignant tumors arising from embryonic remnants of the notochord in axial skeleton. "For example, CXCL13, CXCL14 and CLEC11A promoted inflammatory cell movement; the expression of these molecules in the endophytic chordomas was significantly higher than that in exophyticones." (PMID 25793716, 2015).
chronic inflammatory demyelinating polyneuropathy (1 paper, 2025). "Notably, levels of CLEC11A are elevated in the CSF of patients with chronic inflammatory demyelinating polyneuropathy and in the blood of patients with chronic spinal cord injuries over time, suggesting its potential involvement in chronic neurodegenerative processes." (PMID 40294019, 2025).
diabetes (1 paper, 2023). "CLEC11A, therefore, may provide a novel therapeutic target for maintaining beta-cell function in patients with diabetes." (PMID 37078556, 2023).
lung adenocarcinoma (1 paper, 2024). A carcinoma that arises from the lung and is characterized by the presence of malignant glandular epithelial cells. "C-type lectin domain family 11 member A (CLEC11A), also known as stem cell growth factor (SCGF), promotes the proliferation of hematopoietic progenitor cells in the hematopoietic microenvironment and is involved in lung adenocarcinoma (LUAD) tumorigenesis by promoting tumor angiogenesis." (PMID 37597212, 2024).
melanoma (1 paper, 2025). A malignant, usually aggressive tumor composed of atypical, neoplastic melanocytes. "We identified dozens of melanoma-increased genes uniquely down-regulated by ZDL, including C-type lectin domain containing 11A (CLEC11A), intermediate filament family orphan 1 (IFFO1), and AE binding protein 1 (AEBP1)." (PMID 40141086, 2025).
mental disorder (1 paper, 2023). A disease that has its basis in the disruption of mental process. "Notably, we identified significant associations for CLEC11A and MOB1A, genes known to be associated with immune and mental disorders." (PMID 37012247, 2023).
Obesity (1 paper, 2023). Accumulation of substantial excess body fat. "In contrast, our previous study carrying out RNAseq analysis in mouse pancreas found that obesity reduced the expression level of Clec11a and that the rhCLEC11A plays a regulatory role in proliferation and lipid metabolism in mouse islets." (PMID 37078556, 2023).
trigeminal neuralgia (1 paper, 2025). Trigeminal neuralgia is a nerve disorder that causes a stabbing or electric-shock-like pain in parts of the face. "Furthermore, CLEC11A expression in the CSF is increased in patients with trigeminal neuralgia, indicating that CLEC11A may promote peripheral nerve inflammation, demyelination, and neurodegeneration." (PMID 40294019, 2025).
cancer (16 papers, 2011 to 2025). A tumor composed of atypical neoplastic, often pleomorphic cells that invade other tissues. "CLEC11A, as a member of the C-type lectins superfamily, plays a crucial role in tumor growth and is associated with the prognosis of cancer patients." (PMID 37597212, 2024). "It is likely that the loss of CLEC11A is bearable for a living organism, and that targeting the CLEC11A over-produced by cancers is a potential treatment strategy." (PMID 35267664, 2022). "Despite the proven role of CLEC11A in the progression of various cancers, the underlying mechanism of CLEC11A remains unclear in GC, especially regarding its role and function in tumor immunity." (PMID 38348052, 2024). "Our analysis revealed that CLEC11A exhibited a significant upregulation in various cancers, including GC (p<0.001)." (PMID 38348052, 2024). "The analysis indicated significant enrichment in immune-related and cancer-related pathways for the high CLEC11A expression group." (PMID 37597212, 2024). "To identify the CLEC11A expression in pan-cancer, we used TCGA RNA-seq data to determine the differential expression of CLEC11A in tumor tissues compared to normal tissues." (PMID 38348052, 2024). "GSEA results demonstrated that ECM–receptor interaction, the Hedgehog signaling pathway, and pathways in cancer were closely correlated with the high CLEC11A phenotype." (PMID 37597212, 2024). "These conflicting reports indicate that further studies are needed to elucidate the role of CLEC11A in cancer, with specific attention to the role of methylation." (PMID 38466706, 2024). "The C-type lectin domain family 11 member A (CLEC11A) is part of the C-type lectin superfamily, and its dysregulation has been implicated in the progression of several cancers." (PMID 37597212, 2024). "The evidence provided in our study warrants further studies of the role of CLEC11A in tumor angiogenesis and the potential of targeting CLEC11A for cancer therapy." (PMID 35267664, 2022). "It is possible that the increase of CLEC11A is a common feature in the progression of various cancers." (PMID 35267664, 2022). "It was likely that cancer cells secreted CLEC11A and attracted endothelial cells sprouting from the nearby pre-existing blood vessels and, subsequently, forming new blood vessels in the growing tumor mass." (PMID 35267664, 2022). "We used the Oncomine database to analyze the variations in CLEC11A mRNA levels in different tumors and normal tissues of multiple cancer types." (PMID 33747924, 2021). "CLEC11A was previously found to be part of a gene set up-regulated in cancer stem cell populations upon therapeutic insult." (PMID 31238876, 2019). "Except for 3 pseudogenes (GUCY1B2, HNRNPA1P33, and TUBA3FP), all of the remaining 15 genes showed the most involvement as tumor suppressor genes in distinct carcinomas, and four genes (TUBGCP2, PLEC, CLEC11A, and BARD1) were associated with AML." (PMID 29299160, 2017). "Recent studies have examined the role of CLEC11A in cancer, including AML." (PMID 38466706, 2024). "Because survival is based on a variety of factors, including classification of the tumor, genetic risk factors, and demographics, it is imperative that we determine what role CLEC11A may have in cancer survival." (PMID 38466706, 2024). "We first investigated the CLEC11A expression in various cancer types using the TIMER2.0 database." (PMID 37597212, 2024). "In addition, the signaling pathways modulated by CLEC11A-related DEGs mainly included FA, proteoglycans in cancer, leukocyte transendothelial migration, ECM–receptor interaction, and complement and coagulation cascade signaling pathways." (PMID 37597212, 2024). "Would it be possible for CLEC11A to be targeted for cancer therapeutic purposes?" (PMID 35267664, 2022). "Taken together, these results indicate that CLEC11A expression might be involved in the progression of various cancers." (PMID 35267664, 2022).